PUS7L (pseudouridine synthase 7 like)
Description:
Pseudouridine synthase that catalyzes pseudouridylation of mRNAs.
Synonyms: DKFZP434G1415
Tractability: PROTAC: ubiquitination databases record sites on it.
Gene: Protein-coding gene on chromosome 12 (43,718,992 to 43,759,193, reverse strand). Ensembl gene ENSG00000129317.
Subcellular location (Human Protein Atlas): Nuclear speckles; Nucleoli
Gene Ontology:
Molecular function: protein binding; pseudouridine synthase activity; RNA binding
Biological process: mRNA pseudouridine synthesis; pseudouridine synthesis; RNA modification
Cellular component: nucleus
Genetic constraint (gnomAD): Loss-of-function variants: 25 observed, 31.74 expected, observed/expected ratio (o/e) 0.79, 90% interval 0.57 to 1.1. The upper end of that interval is the gene's LOEUF score, 1.1, which puts it in group 4 of 6, group 1 being the genes least tolerant of losing a copy. Missense variants: 625 observed, 675.26 expected, observed/expected ratio (o/e) 0.93, 90% interval 0.87 to 0.99. Synonymous variants: 221 observed, 233.61 expected, observed/expected ratio (o/e) 0.95, 90% interval 0.85 to 1.06.
Homologues: Orthologues: chimpanzee PUS7L (99% identical), macaque PUS7L (85% identical), dog PUS7L (84% identical), guinea pig PUS7L (82% identical), pig PUS7L (82% identical), mouse Pus7l (72% identical), rat Pus7l (72% identical), rabbit PUS7L (65% identical), tropical clawed frog pus7l (50% identical), zebrafish pus7l (45% identical), Caenorhabditis elegans B0024.11 (22% identical). Paralogues in human: PUS7 (24% identical).
Diseases named in the same sentence as PUS7L in open-access papers:
PUS7L is named in the same sentence as 5 diseases in open-access papers, as found by Europe PMC text mining. Sharing a sentence is not in itself a finding about the gene and the disease. The quoted sentences say what the papers report.
Intellectual disability (1 paper, 2020). "We propose PUS7L and TWF1 as likely candidate genes on the telomeric region of 12q12 for the intellectual disability and craniofacial anomalies seen in DCP250361." (PMID 31963867, 2020). "Additionally, we suggest PUS7L and TWF1 as candidate genes for intellectual disability and craniofacial anomalies on the telomeric region of 12q12." (PMID 31963867, 2020).
Tumor (1 paper, 2023). "We initially calculated the univariate and multivariate analysis of overall survival (OS) rate, including the expression of genes belonging to the PUS family (PUS1, PUS3, PUS7, PUS10, PUS7L, PUSL1), patients’ age, gender, race and Tumor Node Metastasis (TNM)-stage, and set grade as co-variate." (PMID 37315299, 2023).
PUS7L also shares sentences with these, for which no sentence is quoted: prostate adenocarcinoma (1 paper); Sepsis (1); uterine corpus endometrial carcinoma (1).